EHMT2 (euchromatic histone lysine methyltransferase 2)
Diseases named in the same sentence as EHMT2 in open-access papers (continued):
Sharing a sentence is not in itself a finding about the gene and the disease.
pancreatic adenocarcinoma (1 paper, 2022).
prostate tumour (1 paper, 2020). "Likewise, in prostate tumour cells, direct methylation of KDM1A by the protein-methyltransferase EHMT2 facilitates an interaction between the chromatin remodeling proteins CHD-1 and KDM1A, that is necessary for androgen receptor dependent transcriptional activation." (PMID 33068438, 2020).
psoriasis (1 paper, 2023). An autoimmune condition characterized by red, well-delineated plaques with silvery scales that are usually on the extensor surfaces and scalp. "In order to uncover the explicit function of EHMT2 on psoriasis, we generated keratinocyte specific knock-out of Ehmt2 mouse by means of crossing mice with loxP-flanked Ehmt2 alleles (Ehmt2fl/fl) with Keratin14-Cre (K14) mice to delete Ehmt2 in keratinocytes, and testified its efficiency." (PMID 37739945, 2023). "On the basics of showed proof, we illustrated that diminishing the expression of EHMT2 or inhibiting the function of EHMT2 is correlated with ameliorated symptom in psoriasis." (PMID 37739945, 2023). "Based on researched all above, our closer investigation of the relationship between G9A function in keratinocytes and psoriasis now revealed that genetic ablation of EHMT2 gene in keratinocytes provoked anti-proliferation effect and attenuated psoriatic dermatitis." (PMID 37739945, 2023). "Thus, in order to clarify the correlation between EHMT2 and psoriasis, starting with the clinical phenomenon, we found that the expression of EHMT2 was upregulated in lesion skin samples derived from psoriasis patients compared with healthy human skin samples, according to GEO database." (PMID 37739945, 2023). "However, the characteristic of EHMT2 on modifying prognosis of psoriasis remains undetermined." (PMID 37739945, 2023).
schistosomiasis (1 paper, 2023). An infectious disease caused by parasitic trematodes of the genus Schistosoma that colonize human blood vessels and release eggs that can cause granulomatous reactions leading to acute (swimmer's itch or acute schistosomiasis syndrome) or chronic disease. "This ultimately led to the identification of H3K27me3 methyltransferases G9a (KMT1C, EHMT2) and EZH2 (KMT6) inhibitors as development-arresting compounds and potential drugs to treat schistosomiasis." (PMID 37981859, 2023).
serous carcinoma (1 paper, 2023). "We pinpointed SNS-032 and EHMT2 inhibitors BIX-01294 and UNC0646 as therapeutic candidates in high-grade serous carcinoma, as well as probed the efficacy of specific inhibitors in vitro." (PMID 37120667, 2023).
cancer (227 papers, 2008 to 2026). A tumor composed of atypical neoplastic, often pleomorphic cells that invade other tissues. "Elevated EHMT2 expression has been observed across various cancers and is associated with drug resistance and metastasis." (PMID 39763034, 2025). "EHMT2, which encodes for the G9a protein, has emerged as a potential tumor biomarker of aggressive cancers." (PMID 35710782, 2022). "EHMT2 is overexpressed in many types of cancers, and high EHMT2 expression is associated with a poor prognosis." (PMID 34633777, 2021). "EHMT2 dysfunction has been proved to be involved in the autophagy-associated cell death and EHMT2 inhibition can be an effective threpeutic strategy for cancer treatment." (PMID 28225065, 2017). "We next aimed to determine how TGF-β1, downstream of EHMT2, operates to suppress NK cell-mediated cancer cell eradication." (PMID 41366520, 2026). "We found that the loss of EHMT2 led to increased expression of AZGP1, culminating in the attenuation of TGF-β1, thereby facilitating an enhanced NK cell-mediated eradication of cancer cells." (PMID 41366520, 2026). "This assay confirmed that both the treatment of cancer cells with EHMT2 inhibitors (UNC0642 and A366) and the knockdown of EHMT2 in cancer cells significantly increased NK cell-mediated cytotoxicity in UM cell lines." (PMID 41366520, 2026). "EHMT2 loss increased AZGP1 and decreased TGF-β1 levels, resulting in the autocrine elevation of NKG2D ligands MICB and ULBP3, chemokines in cancer cells, and the paracrine stimulation of NK cell function." (PMID 41366520, 2026). "Similar increases in NK cell-mediated cytotoxicity were observed across various NK cell-to-cancer cell ratios in both EHMT2 inhibitor-treated UM cells and UM cells expressing EHMT2 shRNAs." (PMID 41366520, 2026). "In this study, we identified EHMT2 as a key suppressor of NK cell-mediated anti-tumor immunity across multiple cancer types." (PMID 41366520, 2026). "The implication of EHMT2 in suppressing NK cell-mediated cytotoxicity across various cancer types broadens the potential therapeutic applications of EHMT2 and TGF-β1 inhibitors." (PMID 41366520, 2026). "We next asked if, similar to UM cells, the knockdown of EHMT2 can enhance NK cell-mediated eradication of other cancer cell types." (PMID 41366520, 2026). "EHMT2 also plays an important role in immune regulation by inducing changes in both cancer cells and immune cells." (PMID 41366520, 2026). "EHMT2 inhibitors have shown efficacy in curbing the growth of certain cancer types, highlighting their potential as therapeutic agents." (PMID 39763034, 2025). "EHMT2 is highly expressed in various cancers, and several specific inhibitors have been developed as potential anticancer therapies (30, –, 33)." (PMID 40530850, 2025). "EHMT2 depletion in cancer cells impedes cell growth and significantly reduces tumour expansion by modulating several cellular processes, such as transcription, DNA damage response and repair and RNA processing." (PMID 39763034, 2025). "An enormous body of preclinical literature supports the therapeutic potential of inhibitors targeting G9A/GLP (EHMT2/EHMT1) in cancer and in a variety of other disease contexts, including inflammatory conditions and neurodegenerative disorders." (PMID 39403928, 2024). "BIX-01294 is a small-molecule inhibitor of EHMT2 that inhibits cell proliferation and induces apoptosis of cancer cells in DLBCL and human neuroblastoma." (PMID 38225241, 2024). "TIMER database was used for pan‐cancer analysis of different pain genes (Nav1, EHMT2, SP1, SLC6A4, COMT, OPRM1, OPRD1, CYP2D6, and CYP3A4)." (PMID 38352696, 2024). "Multiple studies have shown that elevated expression of EHMT2 is a common feature in various cancers and hematological malignancies." (PMID 37190128, 2023). "EHMT2 has been reported to modulate cell cycle in cancer cells by specifically regulating the expression of certain genes or the activity of signaling pathways." (PMID 37739945, 2023).
cancer (continued). "To investigate the specificity of EHMT2 inhibition in combination with CFZ, we first verified the regulation of canonical EHMT2 targets such as MYC that has been found to be modulated in multiple type of cancers." (PMID 37190128, 2023). "Both EHMT1 and EHMT2 are aberrantly expressed in various cancers and associated with epithelial–mesenchymal transition (EMT), cancer stemness, and metastasis." (PMID 37663929, 2023). "Histone‐lysine N‐methyltransferase EHMT2 (also known as G9a) is a histone methyltransferase frequently overexpressed in many cancer types, including HCC." (PMID 36896891, 2023). "Accordingly, H3K9-selective methyltransferases, including EHMT2, have multi-faceted and divergent roles in cancer development." (PMID 36142795, 2022). "Among them, our algorithm predicts that EHMT2 and ERCC6 have potential LIR motifs (EHMT2: 262WETV265; ERCC6: 1282VEAE1285), which are disrupted by cancer-associated mutations." (PMID 34059679, 2021). "Studies have proven that inhibiting EHMT2 expression suppressed cell growth and inhibited cancer cell migration and invasion." (PMID 33442400, 2021). "Next, the results of Ki67 staining, as well as MTT, soft-agar and xenograft assays, in wild-type and EHMT2−/− Hep3B and Huh1 cancer stem cells collectively revealed that the elevation of EHMT2 expression is required for the tumorigenesis of HCC." (PMID 34344448, 2021). "The recent publication provides a strong theoretical basis to demonstrate that the dual inhibition of EZH2/EHMT2 methyltransferases can bring more effective prospects for cancer treatment." (PMID 34409024, 2021). "Together, this suggests that EHMT2 overexpression is a relevant cancer characteristic with possible ties to tumorigenesis." (PMID 32028644, 2020). "EHMT2 epigenetically activates the serine-glycine biosynthetic pathway, which is critical for cancer cell survival and proliferation through ribosome synthesis and cell cycle progression." (PMID 32028644, 2020). "Here, we used A366 to inhibit histone lysine methyltransferase G9a (EHMT2), which is an epigenetic regulator that modify key lysine and arginine residues on histones, thereby plays an important role in cancer development and maintenance." (PMID 31338003, 2019). "Genetic knockdown of EHMT2, a histone methyltransferase, reduces cancer cell migration and invasion by regulating the expression of EMT-related markers (E-cadherin, claudin-1, and vimentin)." (PMID 31717460, 2019). "The hypoxia-regulated epigenetic factor G9A (also known as EHMT2), a histone H3 lysine 9 (H3K9) methyltransferase, has been implicated as an important oncogenic driver in multiple cancers." (PMID 29145444, 2017). "EHMT2 is overexpressed in many types of cancers and has been suggested to have possible roles in various aspects of tumorigenesis, including cellular differentiation, proliferation, and EMT." (PMID 27174920, 2016). "Recently, abnormally elevated levels of EHMT2 and H3K9me2 have been observed in many types of human cancers." (PMID 27174920, 2016). "Previous studies have suggested that the histone lysine methyltransferase G9a (EHMT2) is required to perpetuate malignant phenotypes through multiple mechanisms in a variety of cancer types." (PMID 26147105, 2015). "Since TGF-β1 can promote immune evasion by acting on both cancer cells and NK cells, we asked if the conditioned media collected from EHMT2 inhibitor-treated cells or AZGP1- and TGF-β1-expressing cells could influence NK cell-mediated cytotoxicity." (PMID 41366520, 2026). "Previous studies have shown the role of EHMT2 in a variety of cellular processes, including embryonic development and cell differentiation, DNA repair and cell survival, immune regulation and in cancer progression." (PMID 41366520, 2026). "Additionally, EHMT2 loss increased the expression of chemokines such as CXCL10 and CCL27 in cancer cells, promoting NK cell migration." (PMID 41366520, 2026).
cancer (continued). "In particular, EHMT2 has been shown to play important roles in a wide variety of cancer types." (PMID 41366520, 2026). "Additionally, the euchromatin histone lysine methyltransferase (EHMT or G9a) family (including EHMT1 and EHMT2) primarily mediates H3 Lysine 9 dimethylation (H3K9me2) and plays important biological roles in cancers." (PMID 38225241, 2024). "Among them, G9a/EHMT2 and GLP/EHMT1 are crucial for H3K9 methylation, and their dysregulation has been associated with tumor initiation and progression in different types of cancer." (PMID 38997742, 2024). "Silencing EHMT1 or EHMT2 in PC-3 cells also significantly decreased cancer cell migration." (PMID 37663929, 2023). "Previously, it was shown that EHMT2, as a H3K9me1 and H3K9me2 catalyzing enzyme, owns a crucial potential on regulating cell proliferation and was always seemed as a tumor promoting gene in various cancer diseases." (PMID 37739945, 2023). "Furthermore, EHMT2 possesses immunomodulatory effects and is overexpressed in multiple types of cancer." (PMID 37529171, 2023). "BRD4770, an inhibitor of EHMT2/G9a, plays a critical role in several kinds of cancers." (PMID 37306883, 2023). "Indeed, EHMT2 is upregulated in many cancers, including PDAC, in which its expression correlates with shorter times to relapse and survival." (PMID 34249932, 2021). "Recently, the roles of EHMT2 in cancers have been extensively explored by different groups." (PMID 34344448, 2021). "Cancers with elevated expression levels of EHMT2 often show lower expression of some important tumor suppressor genes and epithelial-to-mesenchymal transition (EMT) related genes, so its higher expression may contribute to poor prognosis 13-16." (PMID 33442400, 2021). "Elevated expression of the H3K9 mono- and dimethyltransferase EHMT2 occurs in several cancers." (PMID 34109280, 2021). "Although EHMT2 (also known as G9a) plays a critical role in several kinds of cancers and cardiac remodeling, its function in vascular smooth muscle cells (VSMCs) remains unknown." (PMID 32174799, 2020). "Although EHMT2 has been observed to be highly associated with maintaining cellular homeostasis in several cancer lines, 25, 26 its epigenetic regulation in VSMCs has not yet been elucidated." (PMID 32174799, 2020). "Our data suggest that epigenetic control of EHMT2 could be an important regulator of cancer metabolism in NSCLC cells." (PMID 32028644, 2020). "Although EHMT2 plays a critical role in autophagy of cancer cells, whether EHMT2 participates in autophagy of VSMCs or even affects its survival remains unknown." (PMID 32174799, 2020). "These published results demonstrated that EHMT2 could regulate autophagy and autophagy-related molecules in cancer cell lines, but its role in the cardiovascular system, especially in VSMCs, remains unknown." (PMID 32174799, 2020). "Specifically, the inhibition of EHMT2 and TGF-β1 resulted in increased expression of NKG2D ligands (ULBP3 and MICB) on cancer cells in an autocrine manner, resulting in enhanced NK cell-mediated cytotoxicity." (PMID 41366520, 2026). "Collectively, these results demonstrate that EHMT2-mediated TGF-β1 upregulation in an autocrine manner, inhibits NKG2D ligands (MICB and ULBP3) on cancer cells and, in a paracrine manner, suppresses the cytotoxic ability of NK cells and their migration." (PMID 41366520, 2026). "EHMT2 inhibition enhanced NK cell-mediated cytotoxicity by upregulating AZGP1 and NKG2D ligands, reducing TGF-β1 levels in cancer cells, and relieving TGF-β1-mediated suppression of NK cell function and migration." (PMID 41366520, 2026). "We also demonstrated that small-molecule inhibitors of EHMT2 and TGF-β1 can be used as a strategy for unleashing the immune response against cancer cells." (PMID 41366520, 2026).
cancer (continued). "Histone H3 lysine 9 methylation (H3K9me), which is written by the Euchromatic Histone Lysine Methyltransferases EHMT1 and EHMT2 and read by the heterochromatin protein 1 (HP1) chromobox (CBX) protein family, is dysregulated in many types of cancers." (PMID 37782747, 2023). "G9A (gene name EHMT2), as one of the SUV family of H3K9 methyltransferases, was proved to have impact on prognosis of numerous cancers." (PMID 37739945, 2023). "The expression of EHMT2 and EHMT1 is upregulated in various cancers and is correlated with poor clinical outcomes." (PMID 35740522, 2022). "Among these candidate molecular targets, nine were significantly enriched in all three cohorts, and five of them (TP53BP1, RIPK2, EHMT2, IGFBP3, and HMOX1) have been reported to have cancer- and chemoresistance-promoting activities simultaneously." (PMID 35606881, 2022). "Mechanistically, EHMT2 activity functions to support regenerative properties of KrasG12D tumors and normal AT2 cells—the predominant cell of origin of this cancer." (PMID 35983994, 2022). "G9a (Euchromatic histone-lysine N-methyltransferase 2, EHMT2) is frequently upregulated in different types of cancer." (PMID 36713412, 2022). "In the context of lung, EHMT2 activity functions to support regenerative properties of KrasG12D tumors and normal AT2 cells – the predominant cell of origin of this cancer." (PMID 35983994, 2022). "Enhancer of Zeste Homolog 2 (EZH2) and Euchromatic Histone Lysine Methyltransferase 2 (EHMT2) both maintain repressive H3K27 and H3K9 methylation histone marks, respectively, and are frequently overexpressed in cancer." (PMID 35326684, 2022). "To compare expression patterns of EHMT2 in T-ALL to other cancers and normal cellular states, we analyzed several transcriptional databases, including the Differentiation Map (DMAP), Cancer Cell Line Encyclopedia (CCLE), and primary T-ALL datasets." (PMID 35710782, 2022). "Consistent with this, expression of EHMT2 and CDH10 are inversely correlated in multiple cancer types." (PMID 32292512, 2020). "When the two ratios were compared with each other and tumors were ordered from the highest EHMT2:CDH10 ratio to the lowest, 9 out of 15 cancer types were characterised by a strong inverse correlation between the two genes." (PMID 32292512, 2020). "Taking advantage of TCGA pan-cancer database, EHMT2 and CDH10 expression levels were obtained in cancers for which gene expression data was available for both normal and tumor tissues." (PMID 32292512, 2020). "Median expression of EHMT2 and CDH10 in tumors was compared with their respective expression in normal tissues and the two ratios were then compared with each other in each cancer type." (PMID 32292512, 2020). "One of these modifications is H3K9me2, which is carried out by the methyltransferase EHMT2 that represses the transcription of LC3, WIPI1, DOR, and BNIP3 in cancer cells." (PMID 27174920, 2016). "The findings demonstrate that EHMT2 and TGF-β1 inhibitors could be developed as immunotherapeutic agents, especially for cancers that are resistant to conventional T cell-targeted therapies." (PMID 41366520, 2026). "The findings offer previously undocumented insights into the epigenetic regulation of NK cell-mediated cytotoxicity and pave the way for the translation of EHMT2 and TGF-β1-targeted therapies alone or in combination with other cancer immunotherapeutic agents for cancer treatment in the clinic." (PMID 41366520, 2026). "EHMT1 and EHMT2, homologous SET domain–containing KMTs, have emerged as regulators of cancer metabolism, promoting glycolysis and sustaining serine-glycine biosynthesis in cancer cells." (PMID 39062577, 2024). "Our findings serve as a proof-of-concept that activation of histone methyltransferases, such as EZH2, EHMT2, and SMYD3 might promote hepatocarcinogenesis by inducing enhancer aberration of crucial cancer-related genes." (PMID 35300417, 2022).